STAT6 (signal transducer and activator of transcription 6)
Diseases named in the same sentence as STAT6 in open-access papers (continued):
Sharing a sentence is not in itself a finding about the gene and the disease.
glioma (continued). "Taken together, these findings suggest a role for STAT6 in enhancing cell proliferation and invasion in GBM, which may explain why up-regulation of STAT6 correlates with shorter survival times in glioma patients." (PMID 21595984, 2011). "Based on our in vitro data relating STAT6 expression to increased GBM growth and invasion, we hypothesized that increased STAT6 expression would also correlate with a worse prognosis in glioma patients." (PMID 21595984, 2011). "Data from our study support a previously uncharacterized role of STAT6 in glioma cell survival and suggest that epigenetic restoration of STAT6 with the aid of DNA methyltransferase inhibitors, including 5-aza-2′-deoxycytidine (decitabine), could be applied as therapy for STAT6-silenced glioma." (PMID 31530290, 2019). "Notably, STAT6 levels in GSCs were even lower than those in high-grade glioma tissues." (PMID 31530290, 2019). "RSU-1 is significantly upregulated in more aggressive glioma cell types, and silencing RSU-1 can reduce STAT6 and MMP13 to inhibit invasion." (PMID 39458959, 2024). "Four genes showed a higher fusion rate in OAs included NAB2 (0.4% vs. 4.2%) and STAT6 (0.4% vs. 2.9%) in soft tissue sarcoma and FGFR3 (0.4% vs. 3.1%) and TACC3 (0 vs. 3.0%) in glioma." (PMID 36433963, 2022). "We found that co-culture with glioma cells induced STAT3 and STAT6 phosphorylation, two important signaling molecules controlling M2-like macrophage differentiation in BMDMs." (PMID 27367025, 2016). "In glioma cells, IL-4 signalling involves aberrant activation of STAT3 instead of STAT6 which are known to lead to enhanced cell proliferation, cell survival and angiogenesis in a number of human cancers." (PMID 26370624, 2015). "In order to relate our in vitro findings to actual human patient tumor specimens, we utilized a tissue microarray (TMA) to evaluate STAT6 expression in GBM, healthy brain, and lower grade gliomas by immunohistochemistry (IHC)." (PMID 21595984, 2011). "STAT6 protein expression was analyzed by Western blotting in GBM cell lines and by immunohistochemistry in a tissue microarray (TMA) of glioma patient tissues." (PMID 21595984, 2011). "Negative staining for markers like OLIG-2 and STAT6 further helps rule out other glial tumors such as oligodendrogliomas or other neuronal tumors, confirming the glial origin of the tumor and supporting the diagnosis of ependymoma." (PMID 41522411, 2025). "In contrast, STAT6 expression, which was apparent in non-tumor tissue, was decreased in glioma tissues, exhibiting an inverse relationship with tumor grade." (PMID 31530290, 2019). "Collectively, these results suggest that the effects of transient, low-dose 5-Aza on cell death and the cell cycle are primarily, but not exclusively, dependent on STAT6 re-expression in glioma cells." (PMID 31530290, 2019). "In line with our results, a published microarray-based, high-throughput assessment (GEO DataSet record GDS1962) showed that STAT6 mRNA is reduced in glioma tissues compared with non-tumor tissue." (PMID 31530290, 2019). "In a tissue microarray (TMA) of human glioma patients, glioma tissue specimens consistently exhibited higher STAT6 levels than did non-malignant brain tissue." (PMID 21595984, 2011). "Moreover, the formulation better countered the immunosuppressive glioma microenvironment by reducing M2 macrophage polarization via the suppression of IRF4 transcription and diminished phosphorylation of STAT6, STAT3, and AKT, thereby undermining a key mechanism of glioma immune evasion." (PMID 40284496, 2025). "Studies have shown that STAT6 was expressed in many glioma tissues but not in normal brain tissue." (PMID 34276757, 2021). "Given that various immunotherapies are being actively studied for treatment of advanced glioma, it may be possible that 5-Aza can sensitize GBM cancer cells to immunotherapy, and that STAT6, a critical mediator of chemokine induction, could be a key player in this sensitization mechanism." (PMID 31530290, 2019).
glioma (continued). "Based on the findings, we propose that STAT6 downregulation resulting from DNA methyltransferase (DNMT)-mediated hypermethylation of promoter CpG islands facilitates accumulation of HIF-1α through mTOR activation in hypoxia and consequent enhancement of glioma cell survival." (PMID 31530290, 2019). "We further demonstrated that in at least one GBM cell line, STAT6 exhibited basal activity in the absence of external stimuli- an observation that agrees with the predominantly nuclear localization seen in immunohistochemistry of human glioma tissues." (PMID 21595984, 2011).
atopic dermatitis (26 papers, 2016 to 2025). "Animal experiments have also shown that the protein encoded by STAT6 plays a key role in the formation of retinal structures and mediates ocular atopic dermatitis in mice." (PMID 39408566, 2024). "Our findings build on reports of patients with different de novo germline STAT6 mutations, associated a similar atopic phenotype as seen in our patient including treatment resistant atopic dermatitis, hyper-eosinophilia, eosinophilic oesophagitis and multiple food allergies." (PMID 37316763, 2023). "In a previous study, we found that the Piper nigrum fruit extract reduced TMA-induced allergic dermatitis symptoms via suppression of STAT6 phosphorylation in splenocytes and keratinocytes." (PMID 32392825, 2020). "We identified a novel heterozygous germline mutation STAT6 c.1255G > C, p.D419H leading to overactivity of IL-4 JAK/STAT signalling pathway, in a kindred affected by early-onset atopic dermatitis, food allergy, eosinophilic asthma, anaphylaxis and follicular lymphoma." (PMID 37316763, 2023). "HCIE exerts anti-inflammatory and anti-atopic dermatitis effects in human keratinocytes by modulating the MAPK/NF-κB/NLRP3 inflammasome, JAK1/STAT6 pathway, and skin moisturizing factors." (PMID 40777996, 2025). "IL-4 and IL-13 are closely related to atopic dermatitis, and they activate the intracellular JAK1/STAT6 pathway." (PMID 39599592, 2024). "A GOF STAT6 model (designated STAT6VT) has previously been described in vitro and has been used to study chronic atopic dermatitis in mouse models." (PMID 36884218, 2023).
allergic asthma (24 papers, 2010 to 2025). A asthma with a basis in a pathological type I hypersensitivity reaction. "The unbalance between pro-inflammatory and anti-inflammatory cytokines associated to Th2/Th1/Treg cells is also closely linked gene expression for STAT6, T-bet, and Foxp3 in allergic asthma." (PMID 36685604, 2022). "Imuno TF influenced cellular signaling associated to allergic asthma once downregulated STAT6 expression as well as decreased IL-4, IL-5, and IL-13 in lung and serum." (PMID 36685604, 2022). "Ultimately, Imuno TF mitigated the allergic asthma due to the restoration of balance between the responses of Th1/Th2 as well as Treg cells, and their respective transcription factors the T-bet/STAT6 and Foxp3." (PMID 36685604, 2022). "The efficacy of dupilumab in the treatment of severe allergic asthma and CRS and studies in STAT6-deficient mice highlight the central role of the IL4/IL13-IL4Rα-STAT6 signaling pathway in developing eosinophilic asthma." (PMID 35281012, 2022). "Another surprising finding about IL-10 role in allergic asthma, is the induction of airway fibrosis through IL-13/STAT6 pathway or increased TGF-β production, with mucus hypersecretion." (PMID 32024540, 2020). "This information will support further development of STAT6-IP for the treatment of allergic asthma in humans." (PMID 31118931, 2019). "Sensitized mice with STAT6-deficient eosinophils were protected against mucus overproduction and airway hyperresponsiveness following allergen challenge, highlighting an important role for STAT6 signaling in eosinophils in allergic asthma." (PMID 28791289, 2017). "IL-4 is also known to suppress TH17 development in a STAT-6 dependent manner with IL-4Rα−/− mice producing increased levels of IL-17 in an allergic asthma model." (PMID 23284939, 2012). "In a mouse model of ragweed pollen extract (RWE)-induced allergic asthma treatment with fidarestat prevented the expression of IL-13, phosphorylation of STAT-6 and transformation of epithelial cells to goblet cells in the lung." (PMID 21203431, 2010). "Using an A. niger challenge-based mouse model of allergic asthma, STAT6-deficient mice failed to develop airway hyperresponsiveness and pulmonary eosinophilia." (PMID 35281012, 2022). "The unbalance of Th1/Th2 cells response in allergic asthma shows that the IL-4, IL-5, and IL-13 and its respective transcription factor STAT6 remains intensely upregulated at the expense of a drastic decrease of T-bet levels in the airway of individuals with allergic asthma." (PMID 36685604, 2022). "However, murine models of allergic asthma as well as asthmatic individuals present high levels of STAT6 in airway, while both genic expression of T-bet and Foxp3 are drastically downregulated in lung tissue." (PMID 36685604, 2022). "Two Chinese herbal formulas regulating STAT6 cascades have been identified, namely, Srolo Bzhtang and Banhahubak-tang tablet, which both antagonized airway inflammation and allergic asthma through blocked STAT6 signaling." (PMID 36324680, 2022). "STAT6 activation is required for the development of allergic asthma." (PMID 33945658, 2021). "In addition, chlorogenic acid suppresses pulmonary eosinophilia, IgE production, and Th2-type cytokine production in an OVA-induced allergic asthma through inhibiting activation of STAT6 and JNK." (PMID 23737822, 2013). "In this study, we examined whether Th1 or Th2 cells are important regulators of tenascin-C in experimental allergic asthma utilizing mice with impaired Th1 (STAT4-/-) or Th2 (STAT6-/-) immunity." (PMID 21205293, 2011). "No report has shown a degradation of STAT6 during allergic asthma although the condition, especially when severe, induces autophagy in many cell types including B cells and neutrophils." (PMID 36348405, 2022).
allergic asthma (continued). "Cyanidin-3-O-glucoside (C3G) prevented the progression of allergic asthma in a murine model through STAT6/GATA3 signaling suppression, whereas another cyanidin, procyanidin A2, reduced the expression of CCL26 in human keratinocytes via JAK1/STAT6 signaling." (PMID 35566102, 2022). "To test whether Th1 or Th2 cells are important regulators of tenascin-C expression in experimental allergic asthma, we studied the responses of mice with impaired Th1 (STAT4-/-) or Th2 (STAT6-/-) immunity." (PMID 21205293, 2011). "Since major transcription factors are, also, controlling Th2 cell polarization as STAT6, IRF4 and SOCS1, we are concerned in this section with their role in macrophage polarization only, not generally in allergic asthma." (PMID 32024540, 2020). "In the absence of STAT-6, mice did not develop Th2 responses, Ig class switching to IgE, AHR, mucus hypersecretion and airway eosinophilia upon allergen sensitization and airway challenges, highlighting the essential role of this transcription factor in the pathogenesis of allergic asthma." (PMID 22514638, 2012).
renal fibrosis (24 papers, 2016 to 2025). A final common manifestation of a wide variety of chronic kidney diseases characterized by glomerulosclerosis and tubulointerstitial fibrosis. "Loss of IL-4Rα inhibits STAT6 activation, suppresses bone marrow-derived fibroblasts activation, impairs macrophage M2 polarization, and attenuates renal fibrosis." (PMID 36159833, 2022). "STAT6 signaling is primarily activated by Th2 cytokines such as IL-4 and IL-13 and is associated with the pathogenesis of lung, liver and renal fibrosis." (PMID 34512669, 2021). "Then, we sought to explore whether pharmacological inhibition of STAT6 could alleviate the aberrant lipid metabolism and renal fibrosis caused by UUO." (PMID 35046382, 2022). "Targeting the immune-fibrosis crosstalk, the Signal transducer and activator of transcription 6 (STAT6) inhibitor AS1517499 has been shown to improve renal fibrosis by inhibiting myeloid fibroblast activation." (PMID 41333019, 2025). "STAT6 contributes to renal fibrosis by interacting with the PPARα promoter, suppressing FAO, and supporting MMT." (PMID 39445007, 2024). "Studies have demonstrated the involvement of both the adiponectin/APK and JAK3/STAT6 signalling pathways in the development of experimental renal fibrosis and collagen production by cultured mouse cells undergoing MMT." (PMID 39445007, 2024). "The IL4Rα/JAK3/STAT6 signaling pathway plays an important role in the activation of myeloid fibroblasts, the polarization of M2 macrophages and the development of renal fibrosis." (PMID 39877385, 2024). "And Simvastatin can directly inhibit the STAT6 pathway activated by interleukin-13 (IL-13), thereby inhibiting the activation of myeloid fibroblasts and the development of renal fibrosis." (PMID 37781714, 2023). "Our study has demonstrated that IL-4 receptor α (IL-4Rα)/STAT6 axis play an important role in renal fibrosis." (PMID 36159833, 2022). "Tubular-specific depletion, or pharmacologic inhibitor of Stat6 in mice, and Stat6 knockdown in cultured tubular cells attenuated lipid accumulation and renal fibrosis by enhancing FAO." (PMID 35046382, 2022). "We have previously demonstrated that inhibition of IL-4Rα/STAT6 signaling impairs macrophages M2 polarization and attenuates renal fibrosis." (PMID 36159833, 2022). "In this study, we provide strong in vivo and in vitro evidence demonstrating that activation of tubular STAT6 contributes to lipid accumulation and renal fibrosis by inhibiting FAO in the UUO model." (PMID 35046382, 2022). "Recent data reveal that IL-4Rα/STAT6 signaling pathway drives bone marrow-derived fibroblasts and pro-fibrotic M2 macrophages accumulation in renal fibrosis." (PMID 36159833, 2022). "This evidence supports that JAK3/STAT6 signaling takes a crucial part in renal fibrosis via regulating the MMT." (PMID 35990655, 2022). "Taken together, these simultaneous upregulation of STAT6 activation were observed in the mice with multiple renal fibrotic models, indicating the potential involvement of STAT6 in lipid metabolism and renal fibrosis." (PMID 35046382, 2022). "Phospho-STAT6-positive staining was mainly detected in kidney interstitial cells after folic acid administration, indicating that STAT6 activation occurs during renal fibrosis development in folic acid nephropathy." (PMID 34831280, 2021). "More recently, we have reported that knockout of IL-4Rα inhibits STAT6 activation and suppresses M2 macrophage polarization and renal fibrosis." (PMID 34831280, 2021). "STAT6 exerted a protective role on renal cell apoptosis but promoted renal fibrosis by activating collagen synthesis following UUO." (PMID 34199002, 2021). "We have also shown that JAK3 inhibitor treatment, or the genetic deletion of STAT6, inhibits M2 macrophage populations and monocyte-to-fibroblast transition, thereby suppressing renal fibrosis in a mouse model of obstructive nephropathy." (PMID 34831280, 2021).
renal fibrosis (continued). "In the present study, we examine the effect of pharmacological inhibition of STAT6 with AS1517499 on myeloid fibroblast activation in experimental models of renal fibrosis induced by ureteral obstruction or folic acid." (PMID 34512669, 2021). "In the current study, STAT6 KO mice were used to determine the role of STAT6 in the activation of myeloid fibroblasts and the development of renal fibrosis in a murine model of folic acid nephropathy." (PMID 34831280, 2021). "We have recently shown that JAK3/STAT6 plays a crucial role in the activation of bone marrow-derived fibroblasts and development of renal fibrosis in obstructive nephropathy." (PMID 34512669, 2021). "We have showed that the IL4Rα/JAK3/STAT6 signaling pathway play an important role in the activation of myeloid fibroblast and the development of renal fibrosis." (PMID 34512669, 2021). "In summary, this study demonstrates that STAT6 signaling has an important role in myeloid fibroblast activation and macrophage polarization during renal fibrosis development in folic acid nephropathy." (PMID 34831280, 2021). "In the present study, we used STAT6 knockout (KO) mice to investigate the role of STAT6 in bone-marrow-derived fibroblast activation, macrophage polarization, and the development of renal fibrosis in folic acid nephropathy." (PMID 34831280, 2021). "Taken together, these results have shown that STAT6 plays a critical role in myeloid fibroblasts activation, M2 macrophage polarization, extracellular matrix protein production, and renal fibrosis development in folic acid nephropathy." (PMID 34831280, 2021). "In this study, we evaluated the potential therapeutic role of AS1517499, a potent and selective STAT6 inhibitor, in myeloid fibroblast activation and development of renal fibrosis in two experimental murine models." (PMID 34512669, 2021). "Wild-type mice transplanted with STAT6 null bone marrow cells exhibit fewer bone marrow-derived fibroblasts and develop a lesser degree of renal fibrosis." (PMID 26941655, 2016). "We have found that JAK3/STAT6 signaling pathway is activated during the development of renal fibrosis and plays an important role in bone marrow-derived fibroblast activation, extracellular matrix protein production, and interstitial fibrosis development." (PMID 26941655, 2016). "Additionally, JAK3/STAT6 signaling stimulates bone marrow-derived fibroblasts activation, trigger macrophage to a pro-fibrotic M2-like phenotype in renal fibrosis process." (PMID 36159833, 2022). "In conclusion, our study demonstrates the mechanistic details of STAT6-mediated FAO dysregulation in the progression of renal fibrosis and provides a preclinical rationale for efforts to improve the management of renal fibrosis brought about by FAO dysregulation." (PMID 35046382, 2022). "STAT6-deficient mice or mice treated with a JAK3 inhibitor (CP690,550) had fewer accumulations of bone marrow-derived fibroblasts in the experimental obstructed kidney model and developed less renal fibrosis." (PMID 35990655, 2022). "Thus, in addition to less renal fibrosis, mice with renal tubular-specific-Stat6 KO showed reduction in lipid accumulation with increased FAO." (PMID 35046382, 2022). "In our previous studies, we have shown that Jak3 inhibition, or the genetic disruption of STAT6, suppresses the accumulation of myeloid fibroblasts and the formation of myofibroblasts in the kidney and inhibits the development of renal fibrosis in mice with obstructive nephropathy." (PMID 34831280, 2021). "Therefore, we examined whether AS1517499 can inhibit STAT6 activation and pathogenesis of renal fibrosis in folic acid nephropathy." (PMID 34512669, 2021). "Furthermore, we have shown that knockout of IL-4Rα inhibits STAT6 activation, myeloid fibroblast accumulation and transformation into myofibroblasts, M2 macrophage polarization, and development of renal fibrosis following obstructive injury or folic acid administration." (PMID 34512669, 2021).